PKIB (cAMP-dependent protein kinase inhibitor beta)
Description:
Extremely potent competitive inhibitor of cAMP-dependent protein kinase activity, this protein interacts with the catalytic subunit of the enzyme after the cAMP-induced dissociation of its regulatory chains.
Synonyms: PRKACN2
Tractability: PROTAC: ubiquitination databases record sites on it.
Gene: Protein-coding gene on chromosome 6 (122,471,917 to 122,726,375, forward strand). Ensembl gene ENSG00000135549.
Gene Ontology:
Molecular function: cAMP-dependent protein kinase inhibitor activity
Biological process: positive regulation of telomere maintenance
Cellular component: cytoplasm; nucleus
Genetic constraint (gnomAD): Loss-of-function variants: 2 observed, 6.28 expected, observed/expected ratio (o/e) 0.32, 90% interval 0.13 to 1. That is too few expected variants to judge how well the gene tolerates losing a copy. Missense variants: 92 observed, 93.52 expected, observed/expected ratio (o/e) 0.98, 90% interval 0.83 to 1.17. Synonymous variants: 37 observed, 36.83 expected, observed/expected ratio (o/e) 1, 90% interval 0.77 to 1.32.
Homologues: Orthologues: chimpanzee PKIB (100% identical), macaque PKIB (99% identical), pig PKIB (79% identical), mouse Pkib (74% identical), rat Pkib (59% identical), guinea pig PKIB (56% identical), tropical clawed frog pkib (51% identical), zebrafish pkib (41% identical). Paralogues in human: PKIA (33% identical), PKIG (26% identical).
Diseases named in the same sentence as PKIB in open-access papers:
PKIB is named in the same sentence as 27 diseases in open-access papers, as found by Europe PMC text mining. Sharing a sentence is not in itself a finding about the gene and the disease. The quoted sentences say what the papers report.
prostate carcinoma (6 papers, 2020 to 2025). A carcinoma that arises from epithelial cells of the prostate gland. "More specifically, overexpression of PKIB contributed to castration resistance in prostate cancer through Akt phosphorylation, which was correlated strongly with Gleason grade." (PMID 40778650, 2025). "In prostate cancer (PC), PKIB is notably overexpressed in castration-resistant and aggressive subtypes, where it enhances cell growth and invasion by increasing the kinase activity of PKA-C and the phosphorylation of AKT." (PMID 40593489, 2025). "What is clear is that higher expression of PKIB correlates with increased phosphorylation of AKTSer473 across several different cancer types, including osteosarcoma, breast, lung, and prostate cancers." (PMID 38731883, 2024). "Briefly, PKIβ was found to be overexpressed in androgen-insensitive prostate cancer cells, compared with normal prostate cells and androgen-sensitive prostate cancer cells." (PMID 37830741, 2023). "Hence, overexpression of PKIB was indicative of a poor prognosis and malignant phenotype in patients with prostate cancer." (PMID 40778650, 2025). "PKIβ overexpression resulted in an aggressive phenotype in prostate cancer cells." (PMID 37830741, 2023). "Further, while the exact mechanisms between ERα signaling and the development of castration-resistant prostate cancer are unknown, PKIB may be a part of that missing mechanism between ERα and the development of castration-resistant prostate cancer, whether metastatic or not." (PMID 38731883, 2024). "On the other hand, our findings indicate that PKIB plays a role in the nuclear translocation of PKA-Cα, either by promoting its nuclear import or inhibiting its export, aligning with observations in prostate cancer." (PMID 40593489, 2025). "PKIB(cAMP-dependent protein kinase inhibitor beta) was reported as a key regulator of the PI3K/Akt pathway involved in tumor aggressiveness in NSCLC (non-small cell lung cancer) and prostate cancer." (PMID 33043022, 2020). "Reports suggest that PKIB can promote proliferation and metastasis of NSCLC cells, as well as support malignant transformation of triple-negative breast cancer, promote infiltration of colorectal carcinoma, and support prostate cancer aggressiveness." (PMID 36072791, 2022).
breast carcinoma (3 papers, 2019 to 2024). "Together, the estrogen receptors and androgen receptors are both linked to an increase in PKIB expression, with a correlating increase in proliferation and treatment resistance developing in the breast cancer cells, promoting the EGFR signaling pathway and autophagy." (PMID 38731883, 2024). "An siRNA knockdown of PKIB in this study resulted in a decrease in the proliferation of breast cancer cells, thus confirming the role of nuclear estrogen signaling and PKIB in the proliferative potential of breast cancer." (PMID 38731883, 2024). "The nuclear estrogen receptor alpha (ERα) and cFos, part of the AP1 transcription factor complex, bind to the same region of the PKIB gene and increase protein expression in breast cancer." (PMID 38731883, 2024). "The treatment of Erα-positive breast cancer cells with 17β-estradiol (an estrogen steroidal hormone) increased the expression of PKIB." (PMID 38731883, 2024). "The AP1 complex component cFos also binds to the PKIB gene and increases PKIB expression in breast cancer." (PMID 38731883, 2024). "Alternatively, in lung, prostate, and breast cancers, PKIB expression indicates a highly proliferative cancer with poorer patient outcomes including increased mortality." (PMID 38731883, 2024). "There is accumulating evidence that suggests that endocrine-driven cancers, such as Erα-positive breast cancers, may have a greater sensitivity to PKIB alterations than do other cancer types." (PMID 38731883, 2024).
lung cancer (3 papers, 2021 to 2022). A malignant neoplasm involving the lung. "Recently, PKIB was reported involved in regulating proliferation of non–small cell lung cancer through PI3K/Akt signaling pathway." (PMID 36072791, 2022). "Protein kinase (cAMP-dependent, catalytic) inhibitor beta (PKIB) promotes cell proliferation and has been shown to be upregulated in lung cancer." (PMID 34944753, 2021).
colorectal cancer (2 papers, 2022 to 2024). A primary or metastatic malignant neoplasm that affects the colon or rectum. "In colorectal cancer, PKIB acts as a tumor suppressor, where the loss of PKIB expression is correlated with a decrease in normal mucosa." (PMID 38731883, 2024). "PKIB has been implicated in several different cancer types as a potential target for cancer therapy, including prostate, breast, lung, and colorectal cancers, which account for half of new cancer diagnoses and nearly half the number of cancer deaths each year." (PMID 38731883, 2024). "It would be interesting to see the effect microRNA495 has on other models of PKIB, such as Gerhard’s study highlighting PKIB as a potential biomarker for early breast, lung, ovarian, and colorectal cancers." (PMID 38731883, 2024). "Also noteworthy is that while the majority of research has thus far shown a detrimental effect of PKIB, the opposite effect is seen in colorectal cancer." (PMID 38731883, 2024). "In normal colorectal mucosa, PKIB is highly expressed; however, during the transition from normal mucosa to colorectal cancer, PKIB expression is lost." (PMID 38731883, 2024).
osteosarcoma (2 papers, 2022 to 2024). A usually aggressive malignant bone-forming mesenchymal neoplasm, predominantly affecting adolescents and young adults. "In osteosarcoma, PKIB expression is associated with tumor growth but negatively correlated with metastasis." (PMID 38731883, 2024). "In osteosarcoma, PKIB was linked to the expression of two well-known epithelial–mesenchymal transition proteins, E-cadherin and vimentin." (PMID 38731883, 2024). "With this approach, we identified expression of AIM2 and PKIB as being valuable tools to assess risk in patients with osteosarcoma." (PMID 36072791, 2022). "Furthermore, combined clinical profiles analysis showed that the expression of AIM2- and PKIB- related risk scores was significantly related to the overall survival of patients with osteosarcoma." (PMID 36072791, 2022). "Finally, we constructed a nomogram on the basis of AIM2/PKIB expression–based risk score to predict prognosis of the 1-, 2-, 3-, and 5-year OS of patients with osteosarcoma, offering clinical value for prognosis prediction and support osteosarcoma treatment decision process." (PMID 36072791, 2022). "Thus, hub genes of AIM2 and PKIB were selected to construct the risk signature for osteosarcoma." (PMID 36072791, 2022). "In osteosarcoma, the expression of E-cadherin and vimentin was changed by induced overexpression of PKIB." (PMID 38731883, 2024). "Further, PKIB overexpression significantly decreased the ability of the osteosarcoma cells to migrate and invade adjacent tissues." (PMID 38731883, 2024). "Here, we reported that PKIB promotes the proliferation of high metastatic osteosarcoma cells through Akt signaling pathway." (PMID 36072791, 2022). "All of our results showed that PKIB has potential as targets for osteosarcoma therapy, and the related nomogram provided a useful prognosis prediction model for osteosarcoma." (PMID 36072791, 2022). "Focusing on the six intersection genes and their potential roles, we performed multivariable COX analysis and only identified two hub genes, AIM2 and PKIB, which were related to the metastasis of osteosarcoma." (PMID 36072791, 2022). "Compared with 143-B–GFP group, the cell number of the 143-B–PKIB–GFP cells invaded into the lower chamber of transwell was significantly decreased, indicating that PKIB inhibited the invasion of metastatic osteosarcoma cells." (PMID 36072791, 2022). "To verify the effects of PKIB on migration and invasion of osteosarcoma, we performed wound-healing assay and transwell assay." (PMID 36072791, 2022). "To explore the effects of PKIB on the invasion of metastatic osteosarcoma, we performed transwell assay." (PMID 36072791, 2022). "Overexpressing PKIB in osteosarcoma cells downregulated E-cadherin but upregulated vimentin." (PMID 38731883, 2024). "In addition, the experimental results showed that PKIB significantly inhibits the migration and promotes the proliferation of metastatic osteosarcoma cells through affecting the phosphorylation level of Akt." (PMID 36072791, 2022). "To further explore whether PKIB regulating the proliferation of osteosarcoma cells through PI3K/Akt signaling pathway as well, we performed the Western blot to measure the activation level of Akt." (PMID 36072791, 2022). "To verify whether PKIB was related to the metastasis and survival of osteosarcoma as a hub gene, we performed several experiments." (PMID 36072791, 2022). "The results showed that PKIB significantly inhibited the migration and invasion of osteosarcoma cells, and the Western blot experiments showed that the protein level of E-cad was upregulated and of VIM was downregulated in 143-B cell recombinant expression PKIB." (PMID 36072791, 2022). "In addition, PKIB promoted the proliferation of osteosarcoma cells probably through affecting phosphorylation level of Akt and inhibited the migration and invasion of osteosarcoma cells through affecting the expression of E-cad and VIM." (PMID 36072791, 2022).
osteosarcoma (continued). "In addition, further analysis together with clinical data showed that AIM2 and PKIB were identified as hub genes related to OS of patients with osteosarcoma." (PMID 36072791, 2022). "In addition, the Western blot results showed that the phosphorylation level of Akt was upregulated in 143-B cells overexpressing PKIB, indicating that PKIB promotes the proliferation of osteosarcoma probably through signaling pathway that Akt involved in." (PMID 36072791, 2022). "CCK-8 assay results showed that PKIB promote the proliferation of osteosarcoma." (PMID 36072791, 2022). "However, the mechanism of PKIB regulated the metastasis of osteosarcoma is still unclear." (PMID 36072791, 2022). "Furthermore, we found that PKIB significantly inhibited the migration and metastasis of high metastatic osteosarcoma cells, indicating that PKIB plays important roles in the process of metastasis of osteosarcoma and could be a potential target for osteosarcoma treatment." (PMID 36072791, 2022). "Further analysis on the differences between metastatic and non-metastatic samples revealed six intersection genes—AIM2, RPL22L1, PDPN, PKIB, GZMA, and MDM2—that related to metastasis potential of osteosarcoma and the observed gene expression differences resulted from the changes in methylation." (PMID 36072791, 2022). "In this study, we evaluated DNA methylation profiles combined with gene expression profiles of 21 patients with metastatic osteosarcoma and 64 patients with non-metastatic osteosarcoma from TARGET database and identified PKIB and AIM2 as hub genes related to the metastasis of osteosarcoma." (PMID 36072791, 2022). "We identified that PKIB (protein kinase inhibitor-β) and AIM2 (absent in melanoma 2) were related to the metastasis and survival of osteosarcoma." (PMID 36072791, 2022).
bladder cancer (1 paper, 2025). "In summary, this study elucidates the oncogenic role of PKIB and uncovers a novel MYCN-PKIB-PKA-HSP27 signaling axis in bladder cancer (BLCA), advancing our understanding of PKA-mediated regulatory mechanisms in tumorigenesis." (PMID 40593489, 2025). "This investigation is centered on bladder cancer (BLCA), unveiling an augmented expression of PKIB concomitant with heightened BLCA cell proliferation, migration, and invasion in vitro and augmented tumorigenic potential in an in vivo model." (PMID 40593489, 2025). "In conclusion, our data suggest that high expression of PKIB, regulated by MYCN, mediates reduced HSP27 phosphorylation through inhibition of PKA kinase activity, thereby inducing a malignant phenotype in human bladder cancer." (PMID 40593489, 2025).
bladder tumors (1 paper, 2025). "In our study, we found that the expression of only PKIB was significantly upregulated in BLCA, suggesting that PKIB plays an important role in bladder tumors." (PMID 40593489, 2025).
celiac disease (1 paper, 2022). An autoimmune genetic disorder with an unknown pattern of inheritance that primarily affects the digestive tract. "The most significantly up-regulated genes in celiac disease were TAP1, HLA-E, HCP5, STAT1, GBP1, STAT1, LOC100419583, and GBP4 and the down-regulated ones were IDS, PKIB, FBXO2, OXT, and ADI1." (PMID 36011206, 2022).
Huntington disease (1 paper, 2024). Huntington disease (HD) is a rare neurodegenerative disorder of the central nervous system characterized by unwanted choreatic movements, behavioral and psychiatric disturbances and dementia. "In embryonic models of Huntington’s disease, PKIB was shown to maintain steady levels throughout neuronal developments in wildtype stem cells, but in stem cell models of Huntington’s disease, PKIB expression fluctuated throughout the stages of differentiation." (PMID 38731883, 2024).
Hyperglycemia (1 paper, 2024). An increased concentration of glucose in the blood. "In β-cells, chronic hyperglycemia induces PKIB expression, which further leads to insulin resistance." (PMID 38731883, 2024). "Hyperglycemia promotes PKIB expression, which leads to increased insulin resistance and could have an impact on cancer metabolism." (PMID 38731883, 2024).
irritable bowel syndrome (1 paper, 2024). Irritable bowel syndrome (IBS) is a chronic functional condition of the lower gastrointestinal (GI) tract characterized by abdominal pain or discomfort and disordered bowel habit (diarrhea, constipation, or fluctuation between the two). "Further, the silencing of PKIB was achieved through the induction of microRNA495, which attenuated the PKIB-induced phosphorylation of AKTSer473 in a murine model of irritable bowel syndrome." (PMID 38731883, 2024). "However, there has also been some insight into the role of PKIB in non-cancerous environments, such as embryonic development, metabolism, immune and checkpoint regulation, diabetes development, and even irritable bowel syndrome." (PMID 38731883, 2024).
lenti-virus infection (1 paper, 2022). "First, we recombinantly express the PKIB in 143-B cells by lenti-virus infection, and the Western blot results showed that the PKIB was successfully expressed in 143-B cells." (PMID 36072791, 2022).
non-small cell lung carcinoma (1 paper, 2025). A group of at least three distinct histological types of lung cancer, including non-small cell squamous cell carcinoma, adenocarcinoma, and large cell carcinoma. "Similarly, in non-small cell lung cancer (NSCLC), PKIB is upregulated, leading to increased cell proliferation and tumorigenesis through the activation of the PI3K/AKT pathway." (PMID 40593489, 2025).